GLP1R (glucagon like peptide 1 receptor)
Diseases named in the same sentence as GLP1R in open-access papers (continued):
Sharing a sentence is not in itself a finding about the gene and the disease.
type 2 diabetes (continued). "The aim was to assess the impact of glucagon-like peptide-1 receptor agonists (GLP-1 RA) treatment on the progression of ascending aorta dilatation in patients with type 2 diabetes mellitus (T2DM)." (PMID 41155271, 2025). "Glucagon-like peptide-1 receptor agonists (GLP1-RAs) are a class of medications primarily used for treating type 2 diabetes mellitus (T2DM)." (PMID 40150111, 2025). "Therefore, treatments that embody anti-inflammatory effects in parallel with their primary purpose such as GLP-1R agonists may have much to offer in prevention or amelioration of DR in type-2 diabetic patients." (PMID 40940761, 2025). "The therapeutic potential of GLP-1R and its agonists has reshaped approaches to managing type 2 diabetes mellitus (T2DM), cardiovascular diseases, obesity, and even neurodegenerative conditions." (PMID 41463424, 2025). "Glucagon-like peptide-1 receptor agonists (GLP-1RAs) are widely used to improve glycemic control and induce weight loss in individuals with type 2 diabetes (T2D), yet treatment responses vary significantly among individuals." (PMID 41040428, 2025). "Glucagon-like peptide 1 receptor agonists (GLP1-RAs) or sodium–glucose cotransporter 2 inhibitors (SGLT2is) appear to improve renal outcome in patients with Type 2 diabetes (T2D)." (PMID 39963363, 2025). "Glucagon-like peptide-1 receptor agonists (GLP-1 RAs) have shown a reduction in major adverse cardiovascular events (MACE) among patients with type 2 diabetes mellitus (T2DM)." (PMID 40165866, 2025). "Glucagon-like Peptide 1 receptor agonists (GLP-1RAs) have become a crucial category of treatments for Type 2 diabetes mellitus (T2DM) and obesity." (PMID 41333115, 2025). "We aim to investigate comparative dementia risk associated with glucagon-like peptide-1 receptor agonists (GLP1-RAs), sodium-glucose cotransporter-2 inhibitors (SGLT2i), and dipeptidyl peptidase-4 inhibitors (DPP4i) in adults aged ≥ 60 years with type 2 diabetes." (PMID 41420258, 2025). "Glucagon-like peptide-1 receptor agonists (GLP-1RAs) are increasingly used for type 2 diabetes mellitus (T2DM) due to their multifaceted benefits, including glycemic control and cardiovascular protection." (PMID 41034888, 2025). "Glucagon-like peptide 1 receptor agonists (GLP-1 RAs) represent an important medication class, initially approved for type 2 diabetes mellitus (T2DM) and more recently weight loss." (PMID 40496649, 2025). "Researchers have studied glucagon-like peptide-1 receptor agonists (GLP-1 RAs), including liraglutide, semaglutide, and tirzepatide, which improve glycemic control, promote weight loss, reduce inflammation, and enhance endothelial function in patients with type 2 diabetes." (PMID 40978810, 2025). "Limited data are available on the risk of pancreatic adverse events among people with obesity or type 2 diabetes mellitus (T2DM) initiating glucagon-like peptide-1 receptor agonist (GLP-1 RA)." (PMID 41257737, 2025). "This hypothesis is supported by evidence from an outcome trial comparing different treatment regimens for type 2 diabetes, including glucagon-like peptide-1 receptor agonists (GLP-1RA), sodium-glucose co-transporter 2 inhibitors (SGLT-2i), and insulin monotherapy." (PMID 40251633, 2025). "Glucagon like peptide 1 receptor agonists (GLP-1RA) are medications used as a treatment for type 2 diabetes mellitus (T2DM) and obesity." (PMID 40498168, 2025). "This network meta-analysis assesses whether age or sex are associated with differences in the efficacy of sodium-glucose cotransporter 2 inhibitors, glucagon-like peptide-1 receptor agonists, and dipeptidyl peptidase 4 inhibitors in adults with type 2 diabetes." (PMID 39899304, 2025). "This cohort study evaluates whether older adults with type 2 diabetes and cancer have improved survival when taking glucagon-like peptide-1 receptor agonists (GLP-1RAs) compared with sodium-glucose cotransporter-2 inhibitors and dipeptidyl peptidase-4 inhibitors." (PMID 40679827, 2025).
type 2 diabetes (continued). "In recent years, glucagon-like peptide-1 receptor agonists (GLP-1 RAs) have gained significant attention as effective treatments for type 2 diabetes mellitus (T2DM) and obesity, with emerging potential in renal, pulmonary, and other therapeutic areas." (PMID 39840162, 2024). "Glucagon-like peptide-1 receptor agonists (GLP-1RAs) are indicated for type 2 diabetes mellitus (T2DM) and obesity and show preliminary evidence of efficacy in addiction-related behaviours." (PMID 39529123, 2024). "Liraglutide, a glucagon-like peptide-1 receptor agonist, is effective in the treatment of type 2 diabetes mellitus (T2DM) and obesity." (PMID 39330490, 2024). "In addition, some studies have shown that GLP1R agonists can improve mortality, increase left ventricular ejection fraction, and attenuate the level of brain natriuretic peptide in the patients with type 2 diabetes and HF." (PMID 38782946, 2024). "Glucagon-like peptide-1 receptor agonists (GLP-1 RAs) are an intriguing class of antihyperglycemic drugs for type 2 diabetes mellitus (T2DM)." (PMID 39309475, 2024). "However, whether an improvement in beta-cell function observed in type 2 diabetes after switching from a DPP-4 inhibitor to a GLP-1R agonist is also found in PNDM remains unclear." (PMID 39430732, 2024). "Glucagon-like Peptide-1 receptor agonists (GLP-1 RAs) have emerged as a cornerstone in the management of type 2 diabetes mellitus (T2DM), offering glycemic control with favorable cardiovascular outcomes." (PMID 38730578, 2024). "The role of GLP-1R in type 2 diabetes mellitus (T2DM) is highlighted, emphasizing its pivotal contribution to glucose homeostasis, promoting β-cell proliferation, and facilitating insulin release." (PMID 38801466, 2024). "In recent years, there has been increasing interest in the use of glucagon-like peptide-1 receptor agonists (GLP-1RAs) as innovative drugs for the treatment of type 2 diabetes mellitus (T2DM) and obesity." (PMID 39465848, 2024). "At present, GLP-1R agonists are mainly used in clinical practice for the treatment of type 2 diabetes mellitus (T2DM) and obesity and have become a new class of anti-diabetic drugs." (PMID 39858999, 2024). "Furthermore, GLP-1R activation reduced brain responses to food cues as well as food intake in normoglycemic individuals with obesity and patients with type 2 diabetes and obesity in the insula, amygdala, putamen, and orbitofrontal cortex, brain areas involved in eating behavior and reward." (PMID 38463533, 2024). "Semaglutide is a glucagon-like peptide 1 receptor agonist (GLP1-RA) licensed for type 2 diabetes mellitus (T2DM) and obesity." (PMID 39764175, 2024). "In addition, some studies have shown that GLP1R agonists can improve mortality, increased left ventricular ejection fraction, and attenuate the level of brain natriuretic peptide in the patients with type 2 diabetes and HF13–15." (PMID 38782946, 2024). "Glucagon-like peptide 1 receptor agonists (GLP-1RA) have recently garnered significant interest as a potential therapeutic, attributed to their durable effects in weight loss and glycaemic control in metabolic syndromes, such as obesity and type 2 diabetes mellitus." (PMID 38251405, 2024). "Our empirical focus concerns GLP1R agonists, which have proven effective for the treatment of type 2 diabetes and obesity, and for preventing cardiovascular events in people with type 2 diabetes, with a cardiovascular outcome clinical trial underway in people with obesity." (PMID 38379245, 2024). "Among these glucagon-like peptide-1 receptor agonists (GLP-1 RAs), currently marketed for glycaemic control in type 2 diabetes mellitus (T2DM) and for weight loss, offer a novel mechanism to modify neurotoxicity in individuals at-risk for AD." (PMID 39358806, 2024).
type 2 diabetes (continued). "Thus, while GLP-1R agonists are commonly used for type II diabetes and obesity, there is a growing body of evidence about their role in mediating the effects of other conditions involving inflammatory pathways, including asthma, atherosclerosis, neurogenerative disorders, and myopathies." (PMID 38292961, 2023). "Dulaglutide is a glucagon-like peptide-1 receptor agonist (GLP-1RA) indicated for the treatment of type 2 diabetes mellitus (T2DM)." (PMID 37305431, 2023). "Glucagon-like peptide-1 receptor agonists (GLP-1RA) are widely used for treating type 2 diabetes mellitus (T2DM) as they lower blood glucose more potently than conventional oral drugs and reduce body weight (BW) with less risk of hypoglycemia." (PMID 37103055, 2023). "Sodium glucose cotransporter 2 (SGLT2) inhibitors and glucagon-like-peptide-1 receptor (GLP-1-R) agonists are novel therapeutic agents used for the management of type 2 diabetes mellitus (T2DM)." (PMID 37623335, 2023). "Glucagon-like peptide-1 receptor agonists (GLP-1RAs) have been widely used in treating type 2 diabetes mellitus (T2DM) and obesity in adults, but scientific research about the indication in children and adolescents is scarce." (PMID 37383395, 2023). "Co-localisation analysis applied to both marginal and conditionally independent associations for type 2 diabetes and BMI in the GLP1R locus did not support shared causal variants across these traits (posterior probability of shared causal variants across models: 0.22–0.49%)." (PMID 37171501, 2023). "Incretin mimetics like GLP-1 receptor (GLP-1R) agonists (for e.g., Liraglutide, Semaglutide), were initially developed for the treatment of Type 2 diabetes mellitus (T2DM) and obesity but have demonstrated therapeutic benefit across several domains in WS." (PMID 37900147, 2023). "Sodium-glucose cotransporter-2 inhibitors (SGLT2i) and glucagon-like peptide-1 receptor agonists (GLP-1 RA) are among the emerging classes of antidiabetic medications for the management of type 2 diabetes mellitus (T2DM)." (PMID 36408008, 2022). "They interact with their cognate receptors (GIPR and GLP-1R), which are both members of the class B G protein-coupled receptors (GPCRs) and are already recognized as targets for the treatment of metabolic diseases, such as type 2 diabetes mellitus (T2DM) and obesity." (PMID 35953935, 2022). "Glucagon-like peptide-1 (GLP-1) receptor (GLP-1R) agonists are a group of drugs licensed for the treatment of type 2 diabetes mellitus (T2DM)." (PMID 35970890, 2022). "At present, the effects of Glucagon-Like Peptide 1 Receptor agonists (GLP-1RAs) on arrhythmia in patients with type 2 diabetes mellitus (T2DM) and myocardial infarction (MI) are still unclear." (PMID 36277800, 2022). "On 3 January 2018, the first glucagon-like peptide-1 receptor agonist weekly formulation in China was officially approved by the State Food and Drug Administration, providing a new therapeutic option for improving glycemic control in patients with type 2 diabetes." (PMID 35782875, 2022). "For this reason, GLP-1R agonists, such as exenatide and liraglutide, are effectively used to treat type 2 diabetes mellitus (T2DM)." (PMID 36290663, 2022). "Glucagon-like peptide-1 receptor agonists and dipeptidyl peptidase-4 inhibitors are commonly used treatments for patients with type 2 diabetes mellitus (T2DM)." (PMID 35986429, 2022). "In addition to GIPR signaling, the pathway bias at the GLP-1R may contribute to the efficacy of tirzepatide at improving glucose control and body weight regulation in type 2 diabetes mellitus." (PMID 35333651, 2022). "Due to its beneficial insulinotropic effect, several pharmacological GLP-1R agonists have been successfully developed and marketed for the treatment of type 2 diabetes mellitus (T2DM)." (PMID 34262481, 2021).
type 2 diabetes (continued). "A meta-analysis is presented of cardiovascular outcome trials (CVOTs) comparing glucagon-like peptide-1 receptor agonists (GLP-1RA) versus placebo on cardiorenal outcomes in patients with type 2 diabetes mellitus (T2DM)." (PMID 34526024, 2021). "As an agonist of G-protein coupled receptor (GLP-1R), exendin-4 was confirmed beneficial to both type 2 diabetes mellitus (T2DM) and TBI." (PMID 34899180, 2021). "These actions have been harnessed therapeutically for the treatment of type 2 diabetes (T2D) and obesity, with several pharmacokinetically optimised GLP-1R agonists now in routine clinical use." (PMID 33182425, 2020). "Glucagon-like peptide-1 receptor agonists (GLP-1 RAs) demonstrated good glycemic efficacy in patients with type 2 diabetes mellitus (T2DM) recent years, whereas studies on GLP-1 RAs’ biliary effects were limited." (PMID 32539783, 2020). "Glucagon-like peptide-1 receptor (GLP-1R) agonists have emerged as treatment options for type 2 diabetes mellitus (T2DM)." (PMID 30795583, 2019). "The GLP-1/GLP-1R complex appears to function through an intra-islet paracrine mechanism in diabetic conditions which could explain, at least in part, the mechanism of paradoxical hyperglucagonaemia in type 2 diabetes." (PMID 29487355, 2018). "The injectable glucagon-like peptide-1 receptor agonists (GLP-1 RAs) are widely used in the management of type 2 diabetes mellitus (T2DM)." (PMID 28086882, 2017). "Thus, GLP1R is one of the best-validated drug targets for type 2 diabetes." (PMID 28609478, 2017). "Glucagon-like peptide-1 (GLP-1) receptor (GLP-1R) agonists have emerged as treatment options for type 2 diabetes mellitus (T2DM)." (PMID 26621478, 2015). "Furthermore, although GLP-1R agonists are implemented to treat type 2 diabetes, the responsiveness of the central GLP-1R system to activate BAT to take up TG-derived fatty acids and glucose under central insulin resistance is unknown." (PMID 26254578, 2015). "Hence, we cannot exclude that other areas of the GLP1R may also show differential DNA methylation in type 2 diabetes islets." (PMID 23879380, 2013). "Glucagon-like peptide-1 receptor (GLP-1R) agonists have been investigated for treating type 2 diabetes mellitus (T2DM) since the early 1990s because of their ability to enhance glucose-dependent insulin secretion." (PMID 21167014, 2012). "The long-acting GLP-1 receptor (GLP-1R) agonists exendin-4 (Ex-4) and liraglutide are approved therapeutics for the treatment of type 2 diabetes mellitus (T2DM)." (PMID 22384126, 2012). "Glucagon-like peptide-1 receptor agonists (GLP-1RAs), established therapies for type 2 diabetes and obesity, are increasingly recognized for their potential in neurodegenerative diseases." (PMID 41697753, 2026). "Glucagon-like peptide-1 receptor agonists (GLP-1 RAs), originally developed for glycemic control in type 2 diabetes, have emerged as transformative agents with broad therapeutic applications across multiple organ systems." (PMID 41659089, 2026). "Background/Objectives: Glucagon-like peptide-1 receptor agonists (GLP-1RAs) are increasingly used for the management of obesity and type 2 diabetes, particularly among women of reproductive age." (PMID 42122936, 2026). "Glucagon-like peptide-1 receptor agonists (GLP-1 RAs) have redefined the management of obesity and type 2 diabetes mellitus, producing sustained and clinically meaningful reductions in total body weight alongside significant cardiometabolic benefits." (PMID 42037905, 2026). "Glucagon-like peptide-1 receptor agonists (GLP-1RAs), originally established as cornerstone therapies for type 2 diabetes (T2D) and obesity, have recently gained FDA approval for MASLD." (PMID 41901255, 2026). "Glucagon-like peptide-1 receptor agonists (GLP-1 RAs), originally developed for type 2 diabetes and later approved for weight management, have recently been investigated as a potential strategy to address both nicotine dependence and weight control." (PMID 41789246, 2026).
type 2 diabetes (continued). "Glucagon-like peptide-1 receptor agonists (GLP-1RAs), originally used in type 2 diabetes, have demonstrated neuroprotective and anti-inflammatory effects in preclinical PD models." (PMID 41880197, 2026). "The glucagon peptide 1 receptor (GLP-1R), a class-B-type G protein-coupled receptor (GPCR), is a key therapeutic target for many metabolic disorders, including obesity and type 2 diabetes, due to its central role in glucose homeostasis and insulin secretion." (PMID 42157826, 2026). "Semaglutide, a glucagon-like peptide-1 receptor agonist (GLP-1RA), is widely used to manage type 2 diabetes and obesity." (PMID 42220603, 2026). "The glucagon-like peptide-1 receptor (GLP-1R) is a class B1 G protein–coupled receptor and major therapeutic target in type 2 diabetes and obesity." (PMID 41542774, 2026). "Semaglutide represents a unique therapeutic option for patients with type 2 diabetes mellitus (T2DM), being the first and currently only glucagon-like peptide-1 receptor agonist (GLP-1RA) available in both subcutaneous and oral formulations." (PMID 42278227, 2026). "Pharmacological agonists targeting this family of receptors, particularly GLP-1R, have revolutionized type 2 diabetes (T2D) and obesity treatment, and further roles are emerging in the treatment of other related disorders such as metabolic dysfunction–associated steatotic liver disease (MASLD)." (PMID 41542774, 2026). "Tirzepatide, a dual agonist of the glucagon-like peptide 1 receptor (GLP-1R) and glucose-dependent insulinotropic polypeptide receptor (GIPR), represents a new class of medication for obesity and type II diabetes treatment." (PMID 42219687, 2026). "Glucagon-like peptide-1 receptor agonists (GLP-1RAs), approved to manage conditions such as type 2 diabetes, have been observed to reduce substance use as a secondary effect." (PMID 42111969, 2026). "Glucagon-like peptide-1 receptor agonists (GLP-1RAs), such as semaglutide, are widely recognized for their efficacy in treating metabolic disorders, including type 2 diabetes (T2D) and obesity." (PMID 40309769, 2025). "Dual agonists targeting glucagon-like peptide-1 receptor (GLP1R) and glucose-dependent insulinotropic polypeptide receptor (GIPR) are breakthrough treatments for patients with type 2 diabetes and obesity." (PMID 40830598, 2025). "Glucagon-like peptide-1 receptor agonists (GLP-1 RAs) have emerged as promising agents with demonstrated cardiovascular and nephroprotective effects in type 2 diabetes (T2D) and chronic kidney disease (CKD) patients." (PMID 40026358, 2025). "The milestone discovery of semaglutide, a glucagon-like peptide-1 receptor agonist (GLP-1RA), advanced the management of type 2 diabetes mellitus (T2DM)." (PMID 40805859, 2025). "This review examines the burgeoning therapeutic potential of Glucagon-Like Peptide-1 Receptor Agonists (GLP-1RAs), a class of drugs traditionally used to manage type 2 diabetes mellitus and obesity, as neuroprotective agents." (PMID 41417476, 2025). "For example, activation of glucagon family receptors (GLP1R, GIPR, GCGR) shows therapeutic efficacy in treating type-2 diabetes and obesity; however, these receptors are expressed in multiple tissues." (PMID 41264544, 2025). "Glucagon-like peptide-1 receptor agonists (GLP-1 RAs) are an important class of antihyperglycemic medications approved by the US Food and Drug Administration for the treatment of type 2 diabetes (T2D)." (PMID 40788647, 2025). "Glucagon-like peptide-1 receptor agonists (GLP-1RAs), originally developed for type 2 diabetes and obesity, have recently gained attention for their potential effects on addictive behaviors." (PMID 41552827, 2025). "Glucagon-like peptide 1 receptor agonists (GLP-1 RAs), approved for type 2 diabetes and obesity, are being explored off-label for T1D." (PMID 39707844, 2025).